ETS1 (ETS proto-oncogene 1, transcription factor)
Diseases named in the same sentence as ETS1 in open-access papers (continued):
Sharing a sentence is not in itself a finding about the gene and the disease.
tumor (continued). "Tumour and endothelial cell clusters comprised a relatively large proportion of the total number of cells captured in EGC and AGC tissues, accompanied by changes in ETS1 and EFNA4 in EGC and AGC." (PMID 41162582, 2025). "MiR-193b was demonstrated to negatively regulate tumor migration, invasion and metastasis through targeting urokinase type plasminogen activator (PLAU), dimethylaminohydrolase 1 (DDAH1), cyclin D1 (CCND1) and ETS1 in several cancer cell lines." (PMID 39972491, 2025). "Both EFNA4 and ETS1 were overexpressed in GC tissues, with a negative correlation seen between their expression levels in GC tumour samples, suggesting a regulatory relationship." (PMID 41162582, 2025). "EIF4EBP1, as a target gene of the oncoproteins ETS1 and MYBL2, may influence apoptosis by promoting the survival of tumor cells in unfavorable situations." (PMID 39912562, 2025). "In our study, single-cell sequencing results were used to study the use of tumour cell markers with a high proportion in cancer tissues, as well as EFNA4 and ETS1, in order to construct a prognostic model that can better predict the prognosis of patients with GC." (PMID 41162582, 2025). "Additionally, ETS-1 modulates the expression of cell adhesion molecules, such as ICAM-1, which affects the infiltration of immune cells into the tumour microenvironment." (PMID 40181983, 2025). "ETS1, an ETS family transcription factor, is involved in cell proliferation, apoptosis, differentiation, and migration, and is frequently overexpressed in various cancers, contributing to tumour progression and poor prognosis." (PMID 41162582, 2025). "ETS1 positively influences CD8 + T cell populations, including activated central and effector memory CD8 + T cells, suggesting its importance in the regulation of tumour immunity." (PMID 41162582, 2025). "Only the expressions of ERRFI1, ETS1, NDRG1, and ZMAT3 were detected in the tumor microenvironment." (PMID 37600707, 2023). "The high correlation of ETS1 with ZEB2 in the TCGA BRCA RNA-seq data may confirm its oncogene role, but this is most likely a consequence of their correlations with tumor purity." (PMID 36109686, 2023). "Future studies will also need to investigate if the expression of ETS1 and the other transcription factor genes data suggests some EWS tumor cells express at higher levels than EWS cell lines is a result of heterogenous EWSR1:FLI1/ERG expression and/or due to the transduction of external stimuli." (PMID 38187702, 2023). "ETS1 and ETS2 are also involved in tumor suppression under some situations." (PMID 36760475, 2023). "Interestingly, three published gene expression datasets (microarray) also show positive correlations of ETS1 and COL5A3 expression in EWS tumor samples (R>0.7)." (PMID 38187702, 2023). "Considering the invasive and migratory characteristics of the progenitor cells that express ETS1, we hypothesized that its expression in an EWS cell could promote the movement of such a cell away from the site of primary tumor growth." (PMID 38187702, 2023). "Moreover, expression of ETS-family transcription factors is essential for EC differentiation, with ETS1 and ETS2 affecting tumor angiogenesis and metastasis in the tumor microenvironment, especially in ECs46,47." (PMID 36064747, 2022). "First, the relationship between ETS1 and clinical factors was studied, and no significant changes in age, gender, or tumor stage were found in the majority of cancer types, supporting prior findings." (PMID 35463077, 2022). "ETS1 was upregulated in ECs from tumor compared to non-malignant brain ECs (Student’s t test; p < 0.0001)." (PMID 34867089, 2021). "Other Usp9x substrates in cancer (e.g., Ets-1, MCL-1) may also contribute to the anti-tumor activity of Usp9x inhibition and warrants further assessment." (PMID 33613844, 2021).
tumor (continued). "Tumor samples of Inserm series were predicted in 2 and 4 subtypes molecular classification using a predictor based on nine genes: ADAM19, ETS1, and PDCD1LG2 for C1 and C2; CLDN1, DSC3, and SLC24A3 for C1A and C1B; CHL1, ECM2, and PTPN13 for C2A and C2B subtype prediction." (PMID 32083805, 2020). "In HCC, increased transcriptional activity of MMP7 and ETS1 as compared with adjacent noncancerous liver tissue statistically correlated with tumor progression of HCCs." (PMID 32977498, 2020). "ETS1 is conventionally recognized as an oncogene in most of cancers, which is conflicted with the result of our study that illustrates significantly decreased ETS1 mRNA levels in BRCA tumor samples compared with adjacent normal samples." (PMID 32412047, 2020). "Introduction of a dominant-negative mutant of Ets-1 effectively inhibited growth of tumour cells in culture and neo-angiogenesis in vivo." (PMID 32225120, 2020). "Besides, expressions of ENPP2 and ETS1 were significantly decreased in BRCA tumor samples, and ESPN and RIIAD1 were significantly elevated in BRCA tumor samples compared with adjacent normal samples." (PMID 32412047, 2020). "Moreover, the clinical relevance of this finding is supported by investigation of the tumor material derived from a single patient treated with a combination of BRAF- and MEK-inhibitors resulting in undetectable levels of both ETS1 and TERT during therapy." (PMID 31391125, 2019). "In addition, an in vitro study showed that upregulating MIR193A decreased tumor cell proliferation and migration, at least partly, by directly targeting cyclin D1 (CCND1) and ETS proto-oncogene 1 (ETS1) expression." (PMID 31523496, 2019). "ETS1 showed negative immunoreactivity in all types of cancers while GATA2 showed moderate to strong positive immunoreactivity in all tumor types." (PMID 30809433, 2019). "Taken together our discovery of ETS1 as a biomarker of mesenchymal HNSCC and a master regulator of key EMT genes offers promising new avenues for targeted therapeutic possibilities that are tumor subtype specific." (PMID 31306413, 2019). "In agreement with the role of FGFR1 in promoting cell proliferation and carcinogenesis, a number of iFGFR1-upregulated genes are cancer-driving genes such as ETS1, PIM1, NRG1, MMP1, and FOXQ1, while some iFGFR1-downregulated genes are tumor suppressors such as NR4A1 and GDF15." (PMID 30111373, 2018). "However, inhibition of ETS1 expression enhances chemo-sensitivity to DDP and reversed the activation of NF-κB pathway in 231/DDP cells and subcutaneous transplantation tumor in vivo." (PMID 29950928, 2018). "In addition to PEA3/E1AF, other ETS family proteins like ETS-1 and ETS-2 have also been reported to be involved in tumor metastasis." (PMID 24260201, 2013). "In contrast, MCF7 tumor growth in ovariectomized nude mice with and without Ets1 was strictly dependent upon estradiol." (PMID 23874775, 2013). "Furthermore, ETS-1 is involved in regulating the expression of angiogenic factors, including vascular endothelial growth factor (VEGF) and fibroblast growth factor (FGF), which are critical for angiogenesis and tumor-related vascular development." (PMID 40181983, 2025). "Moreover, TF ETS1 could activate target genes CXCR4 and ZEB1 to trigger metastasis mediated by downstream core signaling cascades through the suppression of tumor inhibitor, miRNA MIR497." (PMID 33802957, 2021). "Due to the connection between MAP kinase cascade and ETS1 activity, this could be part of a negative feedback loop and also indicates that ETS1 might have a role in tumor cells’ migration." (PMID 32679859, 2020). "In addition, given the fact that inhibition of a single pathway by an inhibitor alone is almost impossible to completely suppress tumor growth in vitro and in vivo, we are currently performing experiments to identify crucial survival pathways that are up-regulated under SRC/ETS-1 inhibition." (PMID 31118072, 2019).
tumor (continued). "This network demonstrates that 61 exosomal molecules may affect tumor progression through pathways controlled by key components including MET, Ras, RAF1, Mek, ERK1/2, MITF, BCL2, PI3K, Akt, mTOR, PD-1, KIT, JAK STAT3, or ETS1." (PMID 31681332, 2019). "After classifying each tumor as EMT-High, EMT-Mid and EMT-Low, based on the distribution of EMT Scores, we utilized principal component analysis (PCA) to measure and visualize the variance in gene expression within TCGA HNSCC Tumors as a function of the ETS1 MGS." (PMID 31306413, 2019). "Correlation analysis showed that the expression of αvβ6 and Ets-1 were positively correlated, and their strong stains were always detected at the invading edge of the tumor, weak or no stain always in the center of the tumor." (PMID 25264483, 2014). "Given the tumor suppressor activity of Notch signaling in SCC, Ets1's ability to block to Notch activity may be important for its pro-oncogenic effects." (PMID 24337118, 2013). "Statistical analysis revealed that Ets-1 expression had no obvious correlation with age, pathological types, grade, stage and ascites formation, but had significant correlation with malignancy of the tumor." (PMID 21439064, 2011). "Given that the PI3K-AKT pathway can target ETS1 to promote tumor progression in multiple cancers, and ETS1 has been demonstrated to drive epithelial-mesenchymal transition (EMT), this study hypothesizes that EFNA4 may inhibit the PI3K-AKT signaling axis, thereby counteracting ETS1-mediated EMT." (PMID 41162582, 2025). "Likewise, mRNA levels of three oncogenes, namely ETS1, MDM2, and ARAF, were decreased by C treatment; on the contrary, the growth arrest and DNA-damage-inducible G (GADD45G), a stress-responsive gene involved in tumor suppression, was upregulated in C + AFB1 exposed cells." (PMID 33137966, 2020). "Previous studies have suggested that c-Src phosphorylates ETS1, resulting in increased stabilization of ETS1 as it is not degraded by the E3 ligase COP1, leading to increased tumor progression." (PMID 40356520, 2025). "Own in silico analyses revealed substantial ETS1 and ETS2 expression in non-neoplastic brain and tumor tissue." (PMID 37697350, 2023). "The expression levels of STAT4, ETS1, or ESR1 did not significantly differ between the tumor and control groups." (PMID 35155179, 2021). "In the case of EGFR mutant tumours, DUSP6/MKP-3 loss appears secondary to down regulation of the transcription factor and ERK signalling target Ets1, while the mechanism of DUSP6/MKP-3 down regulation in ELM4–ALK tumour cells was not studied." (PMID 26791049, 2016). "The expression in tumour cells of some of these factors such as basic FGF, ETS-1, and uPA appeared not to be affected by transfer of either the BAI1 or LacZ gene (not shown)." (PMID 11875720, 2002). "Specifically, KLF6, BCL2, ETS1, and PLOD2 could provide insights into tumor biology, hypoxia adaptations, and aggressiveness without invasive biopsies." (PMID 40500522, 2025). "Furthermore, we found that ETS1- and ELK3-interacting target genes were all up-regulated in ADGRL4+ renal tubule cells, and none of them were expressed in para-tumor-derived renal tubule cells." (PMID 38287102, 2024). "ETS1, though not in our list of significantly differentially expressed gene across all tumor types, regulates at multiple levels: at the level of E2F1, FOXM1 and PVT1, but due to its negative immunoreactivity in all tumor types, it may be doing so at gene/mRNA level." (PMID 30809433, 2019).
cancer (250 papers, 2004 to 2026). A tumor composed of atypical neoplastic, often pleomorphic cells that invade other tissues. "Stromal-derived Gln is associated with increased cancer cell invasion through activation of a redox-dependent NRF2/ETS1 signaling axis." (PMID 42121871, 2026). "The Ets‐1 transcription factor plays a primordial role in regulating the expression of numerous genes implicated in cancer progression." (PMID 39778077, 2025). "ETS1 expression was significantly associated with cancer stage, and ETS1 expression in stage III was significantly amplified compared to that in stages I and II." (PMID 41162582, 2025). "In previous studies, increased ETS1 expression has been associated with higher grading, poorer differentiation, and increased invasiveness in cancer cells." (PMID 41162582, 2025). "Given the association between ETS-1 overexpression and the aggressive characteristics of multiple malignancies, it represents a promising therapeutic target in cancer treatment." (PMID 40181983, 2025). "Additional cooperating mutations in known cancer genes (including Nf1, Ep300, Notch1, Sbds, and Ets1) were identified in 5 of the 9 GAB2 mAMLs." (PMID 40773291, 2025). "ETS1 is a transcription factor that acts as a major driver of critical events that occur in advanced cancers and is strongly implicated in the progression of almost all cancers." (PMID 39073752, 2024). "The SCNA comprised focal losses in 8p11.22 including the metallopeptidase genes ADAM18 and ADAM32 in 22% of lFL (q = 1.4E-15) and focal gains affecting 11q24.3 harboring cancer-associated genes ETS1 and FLI1 in 22% of lFL (q = 2E-27)." (PMID 37563306, 2023). "ETS1 mRNA levels were significantly upregulated in HBV-associated HCC cancer tissues relative to the pan-cancers." (PMID 36690646, 2023). "In most tumors, ETS1 showed strong correlation with several immune cells, including T cells, B cells, macrophages/monocytes, cancer-associated fibroblasts (CAFs), and DCs." (PMID 36760475, 2023). "Such DNA binding dynamics can promote the co-association of ETS1 with other oncogenic TFs to drive cancer-specific gene transcription." (PMID 37087499, 2023). "Targeting Ets1 enhanced antitumour effects in multiple immunotherapeutic systems, and ETS1 expression was negatively associated with ICB response in patients with cancer." (PMID 37968405, 2023). "Following that, we constructed an ETS1 PPI network to examine the underlying pathways by which ETS1 contributes to cancer carcinogenesis." (PMID 35463077, 2022). "It has been reported that KDM3A-mediated transactivation of ETS1 occurs via a decrease in H3K9me2 is linked to cancer metastasis." (PMID 35338235, 2022). "Meanwhile, ETS1 expression is linked to grade stage in numerous cancers, including HNSC, KIRC, LGG, and STAD." (PMID 35463077, 2022). "In a previous study, KDM3A- mediated transactivation of ETS1 was shown to occur via the H3K9me2 decrease in the genomic region flanking the promoter and was especially linked to cancer development." (PMID 35338235, 2022). "Ets1 expression is linked to poor survival of some cancers and contributes to the cancer cell invasiveness, EMT, and drug resistance." (PMID 35141153, 2021). "Most importantly, an EHF point mutation identified in cancer cells caused a loss of the capacity to inhibit ETS1-induced phenomena, including upregulation of the ZEB1/2 and EMT phenotypes." (PMID 33712555, 2021). "Most importantly, the L285P mutation in EHF-SF abolishes its function and permits ETS1-mediated ZEB1/2 expression to promote EMT during cancer progression." (PMID 33712555, 2021). "ETS1 has been associated with cancer progression in a broad range of cancer types, where ETS1 expression is often correlated with undifferentiated status, higher invasion and angiogenesis, increased metastasis and drug resistance." (PMID 33333852, 2020).
cancer (continued). "Previously, high levels of ETS1 expression have been closely associated with higher chance of metastatic potential and poor prognosis in various types of cancers." (PMID 32477936, 2020). "ETS proto-oncogene 1 (Ets1), a protein encoded by the human Ets1 gene, has versatile roles during the processes of cancer development." (PMID 33344444, 2020). "Mostly, ETS1 expression is linked to poor survival and contributed to the acquisition of cancer cell invasiveness, EMT (epithelial-to-mesenchymal transition), the development of drug resistance and neo-angiogenesis." (PMID 32677948, 2020). "ETS1 has been reported as an oncogene in previous studies, and in most cancers, ETS1 expression is associated with poor survival." (PMID 31417866, 2019). "ETS1, Ets1 proto-oncoprotein, is a member of the Ets family of transcription factors and is involved in the regulation of several cancer-associated functions, such as ECM remodeling, cell migration, and proliferation." (PMID 31217907, 2019). "Within these carcinomas, ETS1 function has been shown to be associated with a wide range of cellular responses that include increased proliferation, angiogenesis, metastasis and drug resistance." (PMID 31306413, 2019). "ETS1 was known to activate AR, as well as multiple cancer-associated pathways, which resulted in enhanced energy metabolism, cancer cell growth and survival." (PMID 28264478, 2017). "Together these data support the association of MYBL1, IL32, TMEM158 and ETS1 with certain TNBCs and the enrichment of genes involved in immune related processes as differentially associated with the cancers." (PMID 28966727, 2017). "Members of the HGF/c-Met/ETS-1 signaling pathway are expressed in human cancers, and a high level of ETS-1 protein is associated with poor prognosis, disease progression, and metastasis." (PMID 29312607, 2017). "To confirm that PARylation inhibition also causes an increase in Ets-1 transcriptional activity in human cancer cells, we carried out luciferase transactivation assays in HeLa cells with increasing doses of PJ-34." (PMID 23405229, 2013). "Here, we demonstrated that PARylation inhibition causes a strong accumulation of Ets-1 in cancer cells with the same kinetics as those of Ets-1 accumulation under proteasome inhibition." (PMID 23405229, 2013). "Traditionally, the functional importance of Ets-1 over-expression in cancer has been associated with the regulation of matrix-degrading proteases and angiogenic factors." (PMID 21042593, 2010). "In further support that Ets-1 is involved in the regulation of altered cancer metabolism, Ets-1 is associated with the increased expression of many genes involved in glycolysis, glycolytic feeder pathways, and the pentose phosphate pathway." (PMID 21042593, 2010). "Taken together, these repressive functions suggest that Ets-1 is prominently involved in the decreased reliance on oxidative phosphorylation frequently associated with cancer cells." (PMID 21042593, 2010). "Therefore, abnormal ETS-1 expression is associated with various diseases characterized by dysregulated angiogenesis, such as cancer and diabetic retinopathy." (PMID 40181983, 2025). "Dysregulation of Ets-1 has been linked to autoimmune disorders and cancer." (PMID 39861471, 2025). "ETS1 is a nuclear transcription factor implicated in cancer progression and metastasis." (PMID 41462902, 2025). "ETS1 is a transcription factor that is often associated with immune suppression and cancer cell proliferation, whereas EFNA4 may play different roles in immune regulation and intercellular interactions." (PMID 41162582, 2025). "In addition, we demonstrated that PARP-1 inhibition caused a strong accumulation of Ets-1 in cancer cells." (PMID 37686260, 2023).